RETN (resistin)
Diseases named in the same sentence as RETN in open-access papers (continued):
Sharing a sentence is not in itself a finding about the gene and the disease.
colorectal cancer (continued). "Currently, the expression of adipokine resistin in colorectal cancer tissue and its clinical significance remains unclear." (PMID 32420377, 2020). "Additionally, serum resistin levels were reported to be increased in several cancers, such as breast and colorectal cancers." (PMID 27509174, 2016). "Although the role of resistin in colorectal cancer is far from being elucidated, several mechanisms may be involved in explaining these outcomes." (PMID 27642602, 2016). "Taken together, visfatin may act on colorectal cancer cell in an autocrine manner while resistin may act in a paracrine manner." (PMID 24551805, 2013). "Recent studies have indicated that resistin and visfatin, two of these adipokines have high level plasma concentrations in colorectal cancer patients and may be promising biomarkers for colorectal cancer." (PMID 24551805, 2013). "However, the main source of resistin reflecting its increased serum levels in cancers especially in colorectal cancer is still ambiguous." (PMID 24551805, 2013). "Recent study has revealed that resistin and visfatin plasma levels are significantly higher in colorectal cancer patients than control group and thus may be good biomarkers for colorectal cancer." (PMID 24551805, 2013). "In other words, visfatin can affect colorectal cancer cells in an autocrine or paracrine and probably slightly in an endocrine (produced by adipocytes) manner, while resistin plays its possible carcinogenesis role in CRC only through paracrine and endocrine manner." (PMID 24551805, 2013). "Moreover, high serum level of resistin has been found in many tumors including breast, prostate and colorectal cancer which implies its relationship to malignancy." (PMID 24551805, 2013). "The p38 MAPK pathway may be activated when RETN attaches to TLR4 on colorectal cancer cells." (PMID 39839775, 2024). "Two trials were excluded because of one provided box-plot without data to describe distribution of serum resistin concentration and the other reported only odd ratio (OR) and 95% CI of the risk of colorectal cancer; we could not get primary data although we tried to contact the authors." (PMID 27642602, 2016). "Three of 11 studies mentioned the relationship between circulating resistin levels and TNM stages of colorectal cancer." (PMID 27642602, 2016). "The results of this meta-analysis suggested that resistin levels were notably higher in patients with CRC than those in healthy controls, indicating that resistin levels may be positively correlated with risk of colorectal cancer, although there was significant heterogeneity among the studies." (PMID 27642602, 2016). "Seven proteins, TFF3, LCN2, CEACAM5, TFF1, SELE, RETN, and AHCY were found to be upregulated in other databases and also in our UK Biobank where TFF3 and LCN2 were found to be the most significant proteins and were highly expressed in colorectal cancer." (PMID 39839775, 2024). "Seven proteins namely TFF3, LCN2, CEACAM5, TFF1, SELE, RETN, and AHCY proteins of both phases were found to be upregulated in colorectal cancer in human protein atlas database, also were significant in our UK Biobank dataset and had an essential function in CRC." (PMID 39839775, 2024). "Taken together, it can be concluded that while visfatin protein can be synthesized by HCT-116 colorectal cancer epithelial cells, resistin, the other possible CRC biomarker is not expressed by colorectal cancer cells." (PMID 24551805, 2013). "While resistin expression in prostate cancer tissue and cell lines is detectable, our result showed that HCT-116 colorectal cancer cell has no potential to synthesize resistin." (PMID 24551805, 2013). "Taken together, it seems reasonable to consider monocytes and other inflammatory cells, but not the colorectal cancer cells, as the main responsible of the high resistin expression in CRC tissue and plasma level due to the chronic low grade inflammation status in CRC." (PMID 24551805, 2013).
colorectal cancer (continued). "In concordance with an earlier study, our findings showed that colorectal cancer cell line HCT - 116 can not be the source of resistin production in CRC and there may be other cells in cancer stroma secreting this adipokine." (PMID 24551805, 2013). "However, they are not the main source of resistin and the high level of resistin in colorectal cancer may be due to monocytes and other inflammatory cells which increase in proinflammation status of cancer." (PMID 24551805, 2013). "However, the clinical significance of resistin expression in colorectal cancer (CRC) tissues is unclear, and there are no reports of any correlation between resistin and fascin-1." (PMID 32420377, 2020).
gestational diabetes (21 papers, 2015 to 2026). Carbohydrate intolerance first diagnosed during pregnancy. "A study on pregnant women with gestational diabetes showed that a healthy diet and thus a normal blood glucose level was associated with a lower serum resistin level compared to women with high blood glucose levels." (PMID 39796247, 2025). "Several studies have associated high maternal resistin levels with more abdominal fat, and gestational diabetes, while low resistin levels have been associated with preeclampsia, but controversy exists between studies." (PMID 35467263, 2022). "Recent studies associate resistin and visfatin as predictors of gestational diabetes mellitus and also that these adipolines are found in tissues such as adipose, subcutaneous adipose, placenta and cord blood." (PMID 36034841, 2022). "We assessed the association between first trimester leptin, resistin, visfatin, BMI and maternal characteristics and the development of gestational diabetes mellitus in the Ho municipality." (PMID 31836012, 2019). "Furthermore, this study found adiponectin, leptin, resistin and visfatin levels to be significantly associated with gestational diabetes." (PMID 38597653, 2024). "Recent meta-analysis suggests GDM is associated with increased maternal resistin levels, while resutls of another meta-analysis do not indicate a significant change of resitin levels in gestational diabetes." (PMID 32762639, 2020). "While some studies suggest that adiponectin and resistin may be involved in serious complications of pregnancy where disparities also exist—such as gestational diabetes mellitus (GDM) and preeclampsia, underlying ethnic variability has not been described in pregnant women." (PMID 26703679, 2015). "A recent meta-analysis of 18 published studies notes that resistin levels are elevated in maternal circulation in gestational diabetes." (PMID 32762639, 2020). "There were also significant positive correlations between leptin, resistin, and visfatin and gestational diabetes mellitus." (PMID 31836012, 2019). "In contrast to adiponectin and leptin, studies about the regulation of chemerin, visfatin, resistin and apelin in gestational diabetes, preeclampsia and intrauterine growth restriction are limited." (PMID 31505789, 2019). "Lipids and adipokines including leptin, resistin and visfatin play various roles in the pathophysiology of Gestational Diabetes Mellitus (GDM)." (PMID 31836012, 2019). "Moreover, one study each reported adiponectin, leptin, resistin and visfatin levels were significant predictors of gestational diabetes." (PMID 38597653, 2024). "However, it is postulated that elevated levels of resistin in gestational diabetes mellitus may serve to exacerbate the condition." (PMID 39683486, 2024). "Furthermore, resistin plasma levels are increased in women with gestational diabetes." (PMID 30845245, 2019). "Interestingly, plasma and/or tissue expression of chemerin, resistin, visfatin and apelin might be associated with various female reproductive disorders including PCOS syndrome, gestational diabetes, preeclampsia, and uterine growth restriction." (PMID 31505789, 2019). "We studied adipokine plasma levels, SAT gene expression, and DNA methylation of LEP, ADIPOQ, and RETN in adult offspring of women with gestational diabetes (O-GDM, N = 82) or type 1 diabetes (O-T1DM, N = 67) in pregnancy, compared to offspring of women from the background population (O-BP, N = 57)." (PMID 28413567, 2017). "The up-regulation of miR-452 in HUVEC from infants of mothers with gestational diabetes might be a defense mechanism to down-regulate TNFα, CCL2, and RETN in HUVEC." (PMID 31013606, 2019). "The role of leptin, adiponectin, ghrelin, resistin, and IGF-I as appetite regulation molecules is well established, but there have been no general conclusions on their levels in human milk, especially in regard to the occurrence of maternal gestational diabetes." (PMID 38612666, 2024).
gestational diabetes (continued). "However, this augmentation remains controversial, since other studies reported that gestational diabetes does not affect plasma resistin levels." (PMID 30845245, 2019).
osteoarthritis (20 papers, 2009 to 2025). A noninflammatory degenerative joint disease occurring chiefly in older persons, characterized by degeneration of the articular cartilage, hypertrophy of bone at the margins and changes in the synovial membrane. "MR reveals a causal relationship between adipokines, such as adipose transport proteins, leptin, and resistin, and the risk of osteoarthritis; however, the underlying mechanisms are more complex." (PMID 39172202, 2024). "The main findings from the literature highlight the association between osteoarthritis (OA) and elevated serum and synovial levels of leptin, chemerin, visfatin, and high plasma levels of resistin." (PMID 39409194, 2024). "Adipokines adiponectin, leptin, and resistin were analyzed in all groups; however, the only association was observed with adiponectin and those with osteoarthritis." (PMID 29225423, 2017). "Additional research is needed to clarify whether there is some causality between resistin and cartilage degradation and whether adipokines contribute to the marathon related increased risk of osteoarthritis." (PMID 25333960, 2014). "Eight markers were found to be associated with an increased risk of osteoarthritis, including serum testosterone, serum dihydrotestosterone, sex hormone-binding globulin, glycosylated hemoglobin (HbA1c), insulin-like growth factor-binding protein 4, lipocalin, leptin, and resistin." (PMID 39172202, 2024). "In osteoarthritis (OA) synovial cells stimulated by visfatin and resistin, an increase in MMP-1 and MMP-13 expression, along with a decrease in Col2a1 expression, has been observed." (PMID 39409194, 2024). "Resistin is a new adipocytokine involved in the insulin signaling pathway, the pathogenesis of osteoarthritis 23,24, and promoting the proliferation and migration of vascular smooth muscle cells." (PMID 34659568, 2021). "One study which examined adiponectin, leptin, and resistin found that all 3 adipokines were elevated in those with osteoarthritis; however, these patients all had severe osteoarthritis and were significantly older than control participants." (PMID 29225423, 2017). "In fact, in RA, serum, and synovial fluid resistin levels were higher than in osteoarthritis, as well as resistin expression in synovial lining layers." (PMID 25426122, 2014). "A significant level of three adipokines (leptin, adiponectin, resistin) has previously been found in synovial fluid of RA and osteoarthritis patients." (PMID 20017992, 2009). "Additionally, resistin was found at higher levels in the synovium tissue of rheumatoid arthritis patients compared to those with spondyloarthritis or osteoarthritis, and it was directly related to both CRP values and the DAS28 measure." (PMID 39409194, 2024). "Besides that, resistin was found in osteoblasts and osteoclasts from human osteoarthritis osteophytes." (PMID 32410876, 2020). "Resistin may be involved in the pathogenesis of osteoarthritis (OA), but a systematic understanding of the role of resistin in OA is lacking." (PMID 30809105, 2019). "In addition, resistin levels are found to be higher in the serum and synovial fluid of RA patients than in those with osteoarthritis (OA)." (PMID 26063682, 2015). "Similarly, compared with HCs or patients with osteoarthritis, serum resistin levels were increased in patients with RA and positively correlated with inflammatory markers such as ESR, CRP, and disease activity, which determined by measuring disease activity score 28 values." (PMID 35592858, 2022). "The expression of resistin and CAP1 in synovial tissue was stronger in RA than in osteoarthritis (OA)." (PMID 29191223, 2017). "Moreover, high levels of resistin are not exclusive to osteoarthritis." (PMID 39409194, 2024).
chronic kidney disease (19 papers, 2008 to 2025). Impairment of the renal function secondary to chronic kidney damage persisting for three or more months. "Mills and colleagues reported that leptin and resistin are significantly associated with the risk and severity of chronic kidney disease." (PMID 32130282, 2020). "Plasma resistin levels were found to be inversely associated with eGFR in patients with chronic kidney disease." (PMID 28806778, 2017). "The presence of elevated levels of resistin was previously reported in the course of chronic kidney disease." (PMID 24259947, 2013). "The purpose of our study was to investigate the relationship between resistin and CV risk in men with chronic kidney disease not treated with dialysis." (PMID 37048072, 2023). "A study was done to determine the levels of resistin, adiponectin, and other inflammatory markers in subjects with chronic kidney diseases with those of control subjects, and it was found that subjects with chronic kidney diseases have increased levels of resistin and TNF-α." (PMID 24692844, 2014). "The aim of this study was to investigate the relationship between resistin and cardiovascular (CV) risk in men with chronic kidney disease (CKD) not treated with dialysis." (PMID 37048072, 2023). "In non-diabetic patients with chronic kidney disease, a negative correlation between serum resistin concentration and albumin level as a marker of malnutrition was observed, which is consistent with the results of the presented study." (PMID 36978817, 2023). "Visceral adipocytes have been shown to produce an array of adipocytokines that could contribute to endothelial injury in the kidney influencing progression to chronic kidney disease (CKD), such as angiotensinogen, TNF-α, plasminogen activator inhibitor-1, resistin, ghrelin, and leptin." (PMID 31152254, 2019).
Glucose intolerance (19 papers, 2006 to 2025). Glucose intolerance (GI) can be defined as dysglycemia that comprises both prediabetes and diabetes. "We have also investigated the impact of resistin perinatal treatment on the predisposition of offspring to inflammation and glucose intolerance when challenged with HFD." (PMID 30845245, 2019). "Resistin also antagonizes insulin action, causing glucose intolerance, whereas elevated serum resistin levels are associated with IR." (PMID 24829591, 2014). "Although the adipokines leptin and adiponectin improve insulin sensitivity, others contribute to the development of glucose intolerance, including visfatin, fetuin-A, resistin, and plasminogen activator inhibitor-1 (PAI-1)." (PMID 35056647, 2022). "Leptin, resistin and visfatin are significantly increased between 11 and 13 weeks of gestation in pregnant women with glucose intolerance and these biomarkers can be used in combination with maternal characteristics for the early prediction of GDM." (PMID 31836012, 2019). "Resistin is an adipocytokine-derived endocrine hormone that was originally named for its role in impairing the molecular effect of insulin and inhibiting hepatic gluconeogenesis, resulting in glucose intolerance in rodents." (PMID 40699617, 2025). "In addition, serum levels of resistin could be a predictor of postpartum glucose intolerance since the protein levels are higher in patients with GDM and postpartum glucose intolerance compared to patients with only GDM." (PMID 34652617, 2021). "In this study, miR-452 with common target sequence in RETN, TNFα, and CCL2 mRNAs could contribute to worsening glucose intolerance in the IH-condition by up-regulation of RETN, TNFα, and CCL2 mRNAs." (PMID 31013606, 2019).